JAK2 (Janus kinase 2)
Diseases named in the same sentence as JAK2 in open-access papers (continued):
Sharing a sentence is not in itself a finding about the gene and the disease.
tumor (continued). "Tumor-associated macrophages, major components of tumor microenvironment associated with cancer metastasis, induce EMT for colorectal cancer migration and circulating tumor cell-mediated metastasis via JAK2/STAT3/miR-506-3p/FoxQ1 axis activated by IL-6." (PMID 34660694, 2021). "In NB, it was shown that these CAF-like MSCs as well as normal BM-MSCs enhance tumor cell proliferation and survival in vitro and stimulate tumor engraftment and growth in vivo through the JAK2/STAT3 and MEK/ERK1/2 pathways in NB cells." (PMID 33287630, 2021). "We observed a substantial reduction in the phosphorylation of STAT3, JAK1, and JAK2 in the tumor tissues of mice treated with 100 mg/kg of Tris DBA." (PMID 34771643, 2021). "At present, the JAK2 inhibitors are gradually becoming a research hot spot in the field of tumor treatment, especially in hematological malignancies." (PMID 34588425, 2021). "In this work, we adapted mathematical modelling to investigate the role of regulatory cytokines (IFN-β, JAK2) on tumour growth through the corresponding intracellular signalling networks and mutual inhibition mechanism between STAT1 and STAT3." (PMID 34631119, 2021). "IL-6, produced by tumors or tumor-infiltrating cells, binds to its target receptor IL-6R and leads to Jak2/STAT3 activation." (PMID 34833950, 2021). "We further analyzed the phosphorylation status of STAT3, JAK1, and JAK2 proteins in the tumor tissues of the xenograft MM mouse model." (PMID 34771643, 2021). "Combined inhibition targeting both the AR and JAK2/STAT1 resulted in substantial tumor suppression due to the reduction in DNA damage repair ability and increment in apoptosis." (PMID 34746227, 2021). "Conversely, PARK2 overexpression was shown to inhibit tumour growth and angiogenesis via the JAK2/STAT3/VEGF pathway in vivo and in vitro." (PMID 33382511, 2021). "Not only immunogenic neoantigens, but also mutations in immunologically relevant genes, can affect the ability of T cells to identify and kill tumor cell, for example; mutations in JAK1, JAK2, B2M, and STK11genes." (PMID 34319027, 2021). "We found the tumor samples from patients with short-term progression, which account for 28.6% (6/21) of all patients, expressed a higher level of p-JAK2 (p = 0.019)." (PMID 34051805, 2021). "Authors reported that JAK2-specific inhibitors had been shown in reducing tumor growth in TNBC cells, but JAK1/STAT3 inhibitor had little effect, sometimes counteracting the JAK2 specific inhibition on TNBC in an in vivo model." (PMID 35010954, 2021). "Supporting the finding that JAK2/STAT3 suppresses STING in tumor cells, co-administration of IL-6, a JAK2/STAT3 activator, impaired the anti-tumor effects of cGAMP." (PMID 33790360, 2021). "The JAK2/STAT3 signaling pathway has been widely demonstrated to be involved in tumor growth and chemoresistance in various malignancies." (PMID 34496932, 2021). "Another possible explanation is that cancer cells exert genetic mutation in IFN-γ related signaling pathways Janus kinase 1 (JAK1) or Janus kinase 2 (JAK2), which make cancer cells less susceptible to T cell-mediated IFN-γ tumor suppression." (PMID 33514004, 2021). "The tumour‐promoting functions of the JAK2/STAT3 signalling pathway have been well recognized in various malignancies, and JAK2/STAT3 participates in promoting EMT and enhancing the stemness of OSCC." (PMID 33289330, 2021). "Consistent with the in vitro experiments, in nude mice exnografted with MGC 803 cells, galangin inhibited tumor growth and reversed the abnormally expressed proteins, such as p-JAK2, p-STAT3, Bcl-2, cleaved caspase-3, cleaved PARP, and Ki67." (PMID 33981228, 2021).
tumor (continued). "Studies utilizing preclinical models of PC have established that inhibition of the Jak2-Stat5 signaling leads to extensive PC cell apoptosis and decreased tumor growth." (PMID 34680353, 2021). "RPS6-KD suppressed the tumor-sphere formation of GBM cells through the inhibition of p-JAK2 and p-STAT3 and concomitantly downregulated the stemness-related proteins Nestin and SOX2." (PMID 35008473, 2021). "HL is frequently associated with a 9p24.1 genomic amplification that includes the JAK2 locus, as well as with a cytokine-enriched tumor microenvironment." (PMID 34925435, 2021). "JAK2/STAT3 is considered a key signaling molecular pathway that promotes tumor cell growth and progression and participates in tumor metastasis by targeting molecular signals that regulate many of the cancer hallmarks." (PMID 34576006, 2021). "The activation of IL-6/JAK2/STAT3 signaling pathway plays an active role in tumor growth and progression." (PMID 34881181, 2021). "Not only immunogenic neoantigens affect the ability of T cells to identify and kill tumor cell, but mutations in immunologically relevant genes can also do, for example; mutations in JAK1, JAK2, B2M, and STK11genes." (PMID 34319027, 2021). "Although the signaling pathway remained blocked, JAK2 knockdown partly abrogated the DCZ0858-mediated tumor-suppressive effect on cell proliferation and apoptosis." (PMID 32296013, 2020). "Evidence suggests that IL-6, a cytokine known for its pro-tumor behavior via JAK2/STAT3 signaling, can attract neutrophils within an immunosuppressed microenvironment." (PMID 31991796, 2020). "As such, the treatment of MPN with IFN-α probably partially reinstates otherwise-defective tumor immune surveillance, as IFN-α can induce a complete hematological response and significantly reduce both the JAK2-mutated and CALR-mutated allele burden." (PMID 32630667, 2020). "miRNA-590-3p regulates breast cancer cell apoptosis by controlling the expression of important regulators of tumor formation and progression, such as of JAK2, PI3K, MAPK1, and CREB." (PMID 32023813, 2020). "Inhibition of the JAK2/STAT3 signal transduction pathway is expected to be an effective way to inhibit tumor growth and promote tumor cell apoptosis." (PMID 33330321, 2020). "TAMs can promote CRC migration, invasion, and circulating tumor cell (CTC)-mediated metastasis via the JAK2/STAT3/miR-506-3p/FoxQ1 axis, enhancing macrophage recruitment through the production of CCL2 by tumor cells." (PMID 32943996, 2020). "Although the JAK2 V617F mutation is considered to be the major cause of MPN, it has been recently shown that JAK2 V617F positive neoplasms often develop in a background characterized by clonal hematopoiesis and other genetic alterations." (PMID 32150880, 2020). "JAK2 expression was examined by immunohistochemistry in tumor tissues from 62 patients with resectable PDAC for further verification." (PMID 33029256, 2020). "Taken together, the present observations indicated that PRP3 served as a tumor active factor in cSCCs by targeting the JAK2/STAT3 pathway." (PMID 32483193, 2020). "Taken together, these results demonstrate that JAK2/STAT3 signalling participates in OCA‐mediated tumour inhibition." (PMID 33164339, 2020). "LNX1 assists the tumor-suppressive function of LDOC1 by mediating the targeted degradation of activated JAK2 (pJAK2), and resultantly, interferes in the IL-6/JAK2/STAT3 signaling axis." (PMID 33333989, 2020). "The expression of PD-L1 was induced by EGFR and JAK2/STAT1, while the inhibition of JAK2 repressed the upregulation of PD-L1 in tumor cells and enhanced their immunogenicity." (PMID 33603661, 2020). "The JAK2/STAT3 signaling pathway is an evolutionarily conserved signaling pathway and is implicated in the tumor growth and metastasis of OSCC." (PMID 32641093, 2020). "HDAC inhibitors are capable of decreasing JAK2 expression in MPN cells bearing the JAK2V617F mutation, thus decreasing JAK/STAT signalling and inhibiting tumour growth." (PMID 32987782, 2020).
tumor (continued). "JAK2/STAT3 pathway inhibitors can prolong the survival of mice by slowing tumor growth and stromal modification, in addition to altering immune cell infiltration." (PMID 33029256, 2020). "We would also measure FGFR1, LepR, and phospho-Jak2 protein expression in tumor tissue since one shortcoming of our study is that many of our correlations involve mRNA." (PMID 33019728, 2020). "Loss-of-function mutations in JAK1 or JAK2 abrogates response to IFN-γ, desensitizing tumor cells to IFN-induced growth inhibition." (PMID 32111080, 2020). "IL-6/JAK2/STAT3 signaling can down-modulate the antitumor immunity of tumor-infiltrating immune cells because STAT3 negatively regulates the functions of neutrophils, natural killer (NK) cells, effector T cells, and dendritic cells." (PMID 32883032, 2020). "HL is frequently associated with a 9p24.1 genomic amplification that includes the JAK2 locus and with a cytokine-enriched tumor microenvironment." (PMID 31707975, 2019). "Both patients were found to be negative for mutations in erythropoietin, erythropoietin receptor, HIF-1α, janus kinase 2, prolyl hydroxylase, succinate dehydrogenase B/C/D, and von Hippel-Lindau genes in circulating leukocytes and resected tumor tissues." (PMID 31185588, 2019). "Different subtypes were notable for particular molecular pathogenetic features; for example, EBV-positive tumours harboured recurrent PIK3CA mutations, along with amplifications involving JAK2, CD274 (encoding PD-L1) and PDCD1LG2 (encoding PD-L2)." (PMID 31790410, 2019). "While JAK-STAT mutations occur at lower frequencies in solid cancers, the JAK2 V617F mutation has also been observed in non-small cell lung cancer (NSCLC), with GOF mutations being linked to alterations in tumor cell PD-L1." (PMID 31842362, 2019). "miR-216a negatively regulates the expression of JAK 2 and restoration of miR-216a in PDAC cells reduces tumor growth possibly by inhibition of the translation of JAK 2 downstream oncogenes, including survivin, and induces apoptosis." (PMID 31557962, 2019). "MicroRNAs (miRNAs) have a crucial role in regulating the expression of oncogenes and function as tumor suppressors to target JAK2." (PMID 30884772, 2019). "Accumulating evidences shows that activation of the IL-17a/JAK2/STAT3 signalling pathway by growth factors or cytokines plays an active role in tumor growth and progression." (PMID 30616627, 2019). "Together, these results suggest that KLF3 is involved in the tumour growth of A549 and 95D cells through regulating JAK2/STAT3 and PI3K/AKT signalling pathways in vivo." (PMID 30485570, 2019). "Loading a combination of ELTN and FDTN on NPs not only enhances the anti-tumor activity by inhibition of the JAK2/STAT3 signaling pathway, but also diminishes the systemic adverse effects." (PMID 31569687, 2019). "The α7-nAChR was significantly overexpressed in HCC specimens (n = 38) compared to non-tumor liver specimens (n = 19) (~2-fold increase, p = 0.002); this was similar to that of JAK2 (~2-fold increase, p = 2.89 × 10−9)." (PMID 31492006, 2019). "In accordance with the in vitro data, silencing JAK2 reduced the stem cell frequency within the primary tumor to one-third of that of control cells." (PMID 31511084, 2019). "Accumulating evidences indicated that JAK2/STAT3 are involved in tumor angiogenesis, particularly in the regulation of VEGFA." (PMID 30755242, 2019). "Further in vivo studies showed that anlotinib inhibited tumor growth, induced autophagy and suppressed JAK2/STAT3/VEGFA pathway, and CQ enhanced this effect." (PMID 30755242, 2019). "As far as tumor-related factors are concerned, target antigen-positive resistance mainly results from tumor mutations such as those in PTEN and JAK1/JAK2, and this mechanism requires further investigation." (PMID 31824840, 2019).
tumor (continued). "Only in 1 cell was there found a gain of the chromosomal region 9p24.3–9p23, where PTPRD is located, which has been reported to act like a tumor suppressor gene in NB, in addition to other genes, indicated to be related to cancer (i.e., JAK2, RLN2, TYRP1)." (PMID 30791380, 2019). "AZD1480, a selective JAK2 inhibitor, reduced tumor growth, decreased peritoneal dissemination and diminished ascites production in a murine model for advanced EOC." (PMID 31861720, 2019). "Abnormal activation of the JAK2/STAT3 pathway plays critical roles in tumor cell proliferation, invasion, survival, angiogenesis and immunosuppression." (PMID 30857539, 2019). "At 42 days after RT, the combination of JAK2 inhibition with RT successfully delayed tumor growth compared to that achieved with RT alone." (PMID 31511084, 2019). "Tumor cell decreases in JAK2 target genes (Socs3, Egfr) were reported, which indicated that target inhibition was achieved, along with decreases in activated STAT3, which was high at trial commencement in all patients." (PMID 31842362, 2019). "Chromosome 9p contains numerous tumor-associated genes, such as PAX5 at 9p13.2, CDKN2A, CDKN2B, MTAP, IFN, MLLT3, PTPLAD2 at 9p21.3, and JAK2 at 9p24.1." (PMID 31168295, 2019). "IFNyR surface expression on TC1 and B16F10 tumor cells and Jak1 and Jak2 expression was similar in all culture conditions (respectively)." (PMID 31196219, 2019). "Accordingly, co-inhibition of PI3K/mTOR and JAK2 synergistically reduced cancer cell number and tumour growth, and also decreased tumour metastatic spread." (PMID 35582276, 2019). "Supporting our discussion of the importance of the tumor microenvironment in influencing IFNα signaling, these authors provide evidence for altered immune profiles based on tumor pSTAT3 and JAK2 expression." (PMID 31060575, 2019). "These anti-tumor activities arise as a result of disruption in the SHP-1/JAK2/STAT3 signaling pathway." (PMID 31569687, 2019). "JAK2/STAT3 signaling played an essential role in promoting tumor initiation and radioresistance by limiting apoptosis and enhancing clonogenic potential." (PMID 31511084, 2019). "Histological analysis also confirmed the enrichment of CD44v6+ CSCs in remnant tumor tissues following RT, and JAK2 inhibition successfully eliminated these cells either alone or in combination with RT." (PMID 31511084, 2019). "The results of this study suggest that the expression of MMPs in tumor cells is regulated by cell density through the synergistic paracrine mechanism of IL-6 and IL-8 via the JAK2/STAT3 signaling pathway." (PMID 30220965, 2018). "PLA2R1 associated activation of JAK2, estrogen related receptor α (ERRα) signalling, and mitochondrial apoptosis pathways were presented as mediators of the PLA2R1 tumour-suppressive function in MDA-MB-453 cells." (PMID 30542512, 2018). "Increased collagen I deposition in TME makes tumor ECM stiff, stimulating tumor growth by modulating a set of signaling events, such as shifting the balance from prolactin signaling (JAK2/STAT5) toward tumor progression signaling (ERK)." (PMID 30220913, 2018). "We also observed that OP-D was effective in suppressing the expression of STAT3, JAK1, JAK2, and Src phosphorylation in tumor tissues." (PMID 30413072, 2018). "This study reveals that the expression of MMPs is tightly regulated by local tumor cell density through the synergistic signaling mechanism of Interleukin 6 (IL-6) and Interleukin 8 (IL-8) via the JAK2/STAT3 complex." (PMID 30220965, 2018). "The increased presence of adipocytes largely changes the hematopoietic stem cell niche in the BM microenvironment and sets up a niche for tumor cells, increasing their proliferation by IL-6 and Janus Kinase 2 (JAK2)." (PMID 30483273, 2018).
tumor (continued). "Whole exome sequencing of tumours from patients that developed resistance following initial clinical response to PD-1 blockade revealed mutations in Janus kinases 1 and 2 (JAK1/JAK2)." (PMID 29319049, 2018). "In breast cancer, for example, the enrichment of JAK2 and STAT3 mutations in distant metastases relative to the primary tumor suggests their involvement in facilitating tumor progression and dissemination." (PMID 30041675, 2018). "BSK805, a JAK2-specific inhibitor when combined with chemotherapy reduced the tumour growth in mice." (PMID 29298879, 2018). "Another means to enhance the anti-tumor immune response would be to combine JAK2/CALR-vaccines with PD-1 specific mAbs, as treatment with these drugs have been shown to enhance the amount of neo-antigen specific T cells in peripheral blood." (PMID 30327655, 2018). "We then detected the protein expression of p-STAT3 and p-JAK2 in the different tumor groups by immunohistochemical staining." (PMID 29693005, 2018). "In a study, the results showed that JAK2 gene is amplified in TNBC cells treated with chemotherapy when compared with the tumours before the treatment indicating the JAK2 role in chemoresistance of TNBC." (PMID 29298879, 2018). "In particular, the persistent stimulation of IL-6 causes the activation of JAK2 and the subsequent phosphorylation/activation of STAT3, which contributes to tumor growth, chemo-resistance and metastasis." (PMID 29651140, 2018). "As a key component of the JAK2/STAT3/Snail pathway, JAK2 is associated with macrophages on tumor infiltration involved in epithelial-mesenchymal transition." (PMID 29849669, 2018). "The inhibition of JAK2/STAT3 signaling pathway contributed to the anti-tumor effect produced by miR-218." (PMID 30314496, 2018). "CXCL12, CXCR4, JAK2, and STAT3 can not only play significant role in tumor cell or macrophage, but also other cells, such as T lymphocyte, neutrophils, tumor-associated fibroblast, and endothelial cells." (PMID 28630636, 2017). "Phosphorylation of Stat5 and Stat3, which has been reported in various tumor cells following EPO-mediated Jak2 activation was next examined." (PMID 28415825, 2017). "They confirmed these findings in vivo, demonstrating that a JAK2 inhibitor depleted the stroma and resulted in densely packed ductal tumor cells with decreased PSC activation, as well as diminished and altered collagen structures." (PMID 28351381, 2017). "To further support our in vitro result, we inoculated athymic nude mice with MFs and cancer cells, and found that suppression of TGF-β and JAK2/STAT3 signaling by inhibitors reduced tumor size and minimized tumor histopathology in vivo." (PMID 28819126, 2017). "The adaptive pattern of PD-L1 expression in the tumor microenvironment can be further accentuated by amplification of the 9p24.1 locus, which contains PD-L1, −L2 and JAK2, the latter of which is an interferon-gamma-responsive element." (PMID 28344809, 2017). "For instance, IL-6 can contribute to tumor cell survival and upregulate the antiapoptotic genes by driving JAK2/STAT3 signal; IFN-ɤ activates macrophage by JAK-STAT signaling pathway." (PMID 28630636, 2017). "WP1066, a small-molecule, directly process of tumorgenesis and metastasis by inhibiting the phosphorylation of JAK2/STAT3 pathway and the subsequent downstream protein, such as survivin and c-Myc, which are associated with tumor formation." (PMID 28570563, 2017). "To explore the underlying mechanism of Gab2-mediated tumor cell growth and invasion, we determined the influence of the ERK, Akt, and Jak2 pathway inhibitors on the tumor-promoting activity of Gab2." (PMID 28842424, 2017). "QRHX treatment blocked the response of macrophages to tumor signals by suppressing CXCL12/CXCR4/JAK2/STAT3 expression and induced a remarkable decrease of the recruitment of M2 macrophages, suggesting the attenuation of M2 subtype cells function by QRHX." (PMID 28630636, 2017).